RORA (RAR related orphan receptor A)
Diseases named in the same sentence as RORA in open-access papers (continued):
Sharing a sentence is not in itself a finding about the gene and the disease.
diabetes (continued). "We evaluated the potential effect of postnatal expression of RORA in the amygdala on maternal diabetes-mediated gene expression and oxidative stress." (PMID 35027651, 2022). "We conclude that RORA agonist and SOD mimetic reverse maternal diabetes-mediated RORA suppression and oxidative stress in the brain." (PMID 35164690, 2022). "We evaluated the potential effect of maternal diabetes and RORA agonist on gene expression and oxidative stress in IEC cells." (PMID 35164690, 2022). "We established a schematic model for maternal diabetes-mediated ASD development through RORA suppression." (PMID 35027651, 2022). "The results showed that maternal diabetes (STZ/WT) significantly decreased the expression of RORA, CYP19A1, and SOD2 compared to the control (CTL/WT) group, and prenatal RORA deficiency mimicked the effect of maternal diabetes." (PMID 35027651, 2022). "We evaluated the potential effect of maternal diabetes and RORA agonist on gastrointestinal function." (PMID 35164690, 2022). "We first evaluated gene expression from IEC, and the results showed that maternal diabetes (STZ/WT) significantly decreased mRNA levels of RORA, CYP19A1 and SOD2, respectively, compared to the CTL/WT group." (PMID 35164690, 2022). "We first evaluated gene expression in the amygdala, including mRNA and protein levels, and found that maternal diabetes (STZ/P-VEH) significantly decreased the expression of RORA, CYP19A1, and SOD2 compared to the control (CTL/WT) group." (PMID 35027651, 2022). "We conclude that RORA suppression contributes to maternal diabetes-mediated GI symptoms in mouse offspring." (PMID 35164690, 2022). "We conclude that RORA agonist and SOD mimetic reverse maternal diabetes-mediated RORA suppression and oxidative stress in IEC." (PMID 35164690, 2022). "The results showed that maternal diabetes (CTL/WT) significantly increased superoxide anion release to 203% compared to the control (CTL/WT) group, and prenatal RORA deficiency (RORA−/−) treatment further potentiated this effect." (PMID 35027651, 2022). "We then evaluated GI function by intestinal permeability assay, and the results showed that maternal diabetes (STZ/WT) significantly increased intestinal permeability compared to CTL/WT group; RORA deficiency (RORA−/−) either mimicked or worsened this effect." (PMID 35164690, 2022). "We conclude that postnatal expression of RORA in the amygdala reverses maternal diabetes-induced gene expression and oxidative stress in offspring, while RORA knockdown mimics this effect." (PMID 35027651, 2022). "Retinoic acid receptor-related orphan receptor alpha (RORA) plays a key role in the regulation of lipid and glucose metabolism and insulin expression that are implicated in the development of type 2 diabetes mellitus (T2DM)." (PMID 27556492, 2016). "In diabetes melitus, RORα was not upregulated after bone defect due to deficient upstream IGF1‐AMPK signalling, resulting in impaired bone regeneration." (PMID 37051760, 2023). "Male offspring from either the control (CTL) or maternal diabetes (STZ) groups received either vehicle (P-VEH) or lentivirus infusion for either RORA expression (P- ↑ RORA) or RORA knockdown (P-shRORA) at 6 weeks old, and the male offspring were used for animal behavior analysis." (PMID 35027651, 2022). "The results showed that maternal diabetes (STZ/VEH) significantly decreased the mRNA levels of RORA, CYP19A1 and SOD2 (P < 0.0001) compared to the CTL/VEH group; MnTBAP treatment (STZ/MnTBAP) completely, while STZ/SR1078 treatment partly (P < 0.01), reversed this effect." (PMID 35164690, 2022). "Finally, we measured histone 3 methylation on the RORA promoter, and the results showed that the maternal diabetes (STZ/VEH) treatment group displayed significantly increased H3K9me3 modification (P < 0.0001) compared to the CTL/VEH treatment." (PMID 35164690, 2022).
diabetes (continued). "As RORα can be targeted by synthetic ligands, these data suggest that pharmacological modulation of RORα may be useful to treat metabolic syndrome and related diseases such as diabetes and liver diseases." (PMID 28744254, 2017). "The results showed that maternal diabetes (CTL/WT) significantly decreased SYP expression, including mRNA and protein levels, as well as spine density, compared to the control (CTL/WT) group, and prenatal RORA deficiency (RORA−/−) treatment mimicked this effect." (PMID 35027651, 2022). "We then evaluated oxidative stress, and the results showed that maternal diabetes (STZ/WT) significantly increased ROS formation and 3-nitrotyrosin formation, respectively, compared to the CTL/WT group; RORA deficiency (RORA−/−) either mimicked or worsened this effect." (PMID 35164690, 2022). "In addition, we evaluated gene expression in the hypothalamus and hippocampus, and the results showed that maternal diabetes (STZ/VEH) significantly decreased expression of RORA and CYP19A1 in both the hypothalamus and hippocampus compared to the CTL/VEH group." (PMID 35164690, 2022). "Treatment of NOD mice with a selective inverse agonist of RORα/γ, the main transcription factor involved in Th17 differentiation, significantly reduced diabetes incidence, insulitis, and proinflammatory cytokine expression, showing that Th17 differentiation blockade improves experimental diabetes." (PMID 31963845, 2020). "The results showed that the expression of RORA and CYP19A1 was significantly decreased in maternal diabetes (STZ/WT) group compared to the CTL/P-VEH group." (PMID 35027651, 2022). "We conclude that RORA agonist and SOD mimetic reverse maternal diabetes-mediated pre-inflammatory cytokine release in PBMC cells." (PMID 35164690, 2022). "In general, our results indicate that RORA agonist and SOD mimetic reverse maternal diabetes-mediated gastrointestinal dysfunction, including cytokine release, increased intestinal permeability and changes in gut microbial composition." (PMID 35164690, 2022). "Our previous research demonstrated a significant reduction in RORα expression in diabetic hearts, and lack of RORα exacerbated diabetes-induced systolic dysfunction and cardiac remodeling." (PMID 39950114, 2025). "In relation to diabetes, the absence of RORα has been found to markedly heighten diastolic dysfunction and cardiac remodeling in in vivo animal models." (PMID 39518891, 2024). "In the state of diabetes mellitus, RORα fails to upregulate as hyperglycemic inflammatory microenvironment induced IGF1‐AMPK signalling deficiency, leading to impaired bone repair." (PMID 37051760, 2023). "Our results showed that SOD mimetic MnTBAP completely, while RORA agonist SR1078 partly, reversed maternal diabetes-mediated oxidative stress and inflammation in the brain, PBMC and IEC, as well as GI symptoms, including intestine permeability and altered gut microbiota compositions." (PMID 35164690, 2022). "Previous data obtained in the lab have shown that targeting RORα and RORγ with synthetic inverse agonist reduces diabetes in a non-obese mouse model." (PMID 28744254, 2017). "Our result showed that offspring from the maternal diabetes (STZ/VEH) treatment group displayed significantly decreased ultrasonic vocalizations (P < 0.0001) compared to CTL/VEH treatment; both SOD mimetic (STZ/MnTBAP) or RORA agonist (STZ/SR1078) partly reversed this effect (P < 0.01)." (PMID 35164690, 2022). "Moreover, in the hypothalamus, SOD2 mRNA levels did not significantly change in maternal diabetes (STZ/WT) group, while they were significantly decreased in the prenatal RORA deficiency (RORA−/−) group compared to the control (CTL/WT) group." (PMID 35027651, 2022). "This indicates that RORA suppression may play an important role in maternal diabetes-mediated GI symptoms, although this does not exclude other potential factors." (PMID 35164690, 2022).
prostate carcinoma (17 papers, 2011 to 2026). A carcinoma that arises from epithelial cells of the prostate gland. "Other key CCCGs, including BMAL1, CLOCK, PER1/2/3, and RORα, are also shown to be associated with an increased risk of prostate cancer." (PMID 40948103, 2026). "Reduced RORA expression was associated with tumor progression and unfavorable prognosis in cancers, such as prostate cancer, colon, and breast cancer." (PMID 35504868, 2022). "A reduced level of RORα has been associated with several other cancers, including hepatocellular, breast, lung, colon, cervical, ovary and prostate cancers." (PMID 27542227, 2016). "It was reported that aggressive prostate cancer was closely linked with three core circadian clock genes, ARNTL, NPAS2, and RORA." (PMID 34621761, 2021). "In mouse models activation of RORα inhibited growth of androgen-independent prostate cancer cells." (PMID 27542227, 2016). "Besides functioning as cellular regulators of CCCGs, Rorα and Rev‐erbα can regulate murine Ar gene transcription and testosterone levels, suggesting that crosstalk between these NRs could play roles in prostate cancer progression." (PMID 40948103, 2026). "Therefore, we investigated a specific cross-regulation between RORα1, not by RORα4, and Wnt/β-catenin signaling in a prostate cancer cell culture model, a RORα-deficient mouse model, and in clinical samples of patients with prostate carcinomas." (PMID 30987323, 2019). "In affected men, RORA is typically inactivated, and RNASEL is a candidate for the hereditary prostate cancer gene (HPC1)." (PMID 36424644, 2022). "The EVs were taken up by prostate cancer cell lines, and functional in vitro analysis confirmed the regulation of RORA by the identified EV-miRNAs, resulting in dysregulation of proliferation and inflammation, and linking PPAT with prostate cancer aggressiveness." (PMID 39698417, 2024).
atherosclerosis (16 papers, 2011 to 2025). A disease characterized by the build-up of fatty material and calcium deposition in the arterial wall resulting in partial or complete occlusion of the arterial lumen. "The RORα gene encodes a ligand-dependent orphan nuclear receptor that acts as a transcriptional regulator and has been identified as a novel anti-atherosclerosis target gene." (PMID 32321446, 2020). "Retinoic acid receptor-related orphan receptor α (RORα)-deficient mice exhibit several phenotypes indicative of aberrant lipid metabolism, including dyslipidemia and increased susceptibility to atherosclerosis." (PMID 32321446, 2020). "RORα is a potent regulator of a number of genes associated with development of the central nervous system and atherosclerosis." (PMID 31636631, 2019). "The retinoid-related orphan receptor alpha (Rorα)-deficient staggerer (sg/sg) mice display several phenotypes indicative of aberrant lipid metabolism, including dyslipidemia, and increased susceptibility to atherosclerosis." (PMID 26812621, 2016). "Moreover, analysis of the phenotype of the Rorasg/sg mouse has revealed the importance of RORα in regulating the inflammatory and immune responses, in modulating atherosclerosis susceptibility, and in post-ischemic angiogenesis." (PMID 21818335, 2011). "Recent studies have revealed that RORα exerts a protective impact against cardiovascular disorders such as myocardial hypertrophy, myocardial ischemia-reperfusion injury, and atherosclerosis." (PMID 39950114, 2025). "RORs (RORα and RORγ) are known to play a role in atherosclerosis and lymphocytes TH17 differentiation." (PMID 28744254, 2017). "Notably, substantial evidence indicates that RORα influences both pathological and physiological within the cardiovascular system, including myocardial hypertrophy, hypertension, atherosclerosis, myocardial ischemia/reperfusion injury, and hypoxia or ischemia." (PMID 39950114, 2025). "RORα agonist has shown a powerful anti-atherosclerosis effect." (PMID 36834872, 2023). "However, there is accumulating evidence that RORα mediates anti-inflammatory responses in inflammatory diseases, such as sepsis and atherosclerosis." (PMID 31636631, 2019). "In short, RORα activators may have therapeutic prospects in the treatment of atherosclerosis." (PMID 36834872, 2023). "Besides regulating circadian rhythm, RORα also influences a wide range of physiological and pathological processes in the cardiovascular system, including atherosclerosis, hypoxia or ischemia, myocardial ischemia/reperfusion injury, diabetic cardiomyopathy, hypertension, and myocardial hypertrophy." (PMID 36834872, 2023). "It is likely that CLA mediated regulation of both PGC-1α and RORα may regulate Cyb7b1 since it has previously been shown that in RORα−/− mice, which develop severe atherosclerosis, there is suppression of Cyp7b1 expression suggesting RORα may be a positive regulator of Cyp7b1." (PMID 23964012, 2013). "We found several novel activation pathways between d-flow and atherosclerosis, such as Zn2+-dependent inner mitochondrial membrane metalloendopeptidase OMA1, SR 1078 (a selective agonist of RORα and RORγ) and EIF2AK3 (eukaryotic translation initiation factor 2 alpha kinase 3)." (PMID 38646649, 2024). "The ANXA2-R1 rs17845226 SNP has modest LD (r2 ≥ 0.4) with 34 SNPs, all located downstream of the ANXA2 gene-coding region in the long intergenic region between two genes, FOXB and ANXA2 on chromosome 15, and near the RORA and LIPC loci, which play roles in lipid metabolism and atherosclerosis." (PMID 28456096, 2017). "Some of the RORα-modulated genes are involved in physiological functions such as lipid metabolism (LPA, NR1D2, ADIPOQ also known as adiponectin) and inflammation (ADIPOQ, PLG), but also in related cardiovascular diseases such as atherosclerosis." (PMID 21818335, 2011).
atherosclerosis (continued). "Taken together, there is no definitive conclusion about the exact target genes of RORα during atherosclerosis, which might depend on cell types, stimulus properties, stimulation time, surrounding microenvironment, and so on." (PMID 36834872, 2023).
glioma (16 papers, 2011 to 2025). A benign or malignant brain and spinal cord tumor that arises from glial cells (astrocytes, oligodendrocytes, ependymal cells). "Our previous studies also demonstrated that RORA inhibits the proliferation and tumorigenesis of glioma via inhibiting the TNF-α-mediated NF-kB signaling pathway." (PMID 35945192, 2022). "In human glioma cell lines and glioma stem cells, RORα overexpression inhibits proliferation and tumorigenesis by inhibiting the TNF-α-mediated NFκB signaling pathway." (PMID 35605663, 2022). "Previously, RORα overexpression abrogated glioma tumorigenesis through reducing TNF-α-mediated NF-κB signaling." (PMID 35440077, 2022). "Sev blocked the progression of glioma by increasing circRELN expression, and circRELN played roles in glioma partly by regulating the miR-1290/RORA network." (PMID 34479497, 2021). "We first detected the expressions of RORA in 87 clinical glioma specimens and 18 normal brain tissues using RT-qPCR, western blotting, and immunohistochemical staining." (PMID 34408982, 2021). "The expression of RORA was notably downregulated in glioma tumor tissues compared to normal tissues." (PMID 34479497, 2021). "In our previous study, RORA was confirmed as a suppressor in glioma, which inhibited the proliferation and tumorigenesis of glioma cell lines and GSCs." (PMID 34408982, 2021). "Our previous study showed that RORA played an anti-tumor role and inhibited the tumorigenesis and proliferation in glioma." (PMID 34408982, 2021). "In summary, Sev plays an important role in blocking the development of glioma by increasing the expression of circRELN, and we find that circRELN governs the miR-1290/RORA axis in its networks." (PMID 34479497, 2021). "The role of RORA was also partly explored in glioma, and RORA overexpression inhibited proliferative capacity and tumorigenesis in glioma." (PMID 34479497, 2021). "Overall, we define that Sev blocks glioma malignant development by upregulating circRELN through circRELN-mediated miR-1290/RORA axis." (PMID 34479497, 2021). "Further analysis showed that circRELN played biological functions in glioma by upregulating RORA via competitively targeting miR-1290, which was demonstrated by rescue experiments." (PMID 34479497, 2021). "Our previous study found that retinoic acid receptor-related orphan receptor A (RORA) is a nuclear receptor and plays an important role in inhibiting proliferation and tumorigenesis of glioma." (PMID 34408982, 2021). "Our study exhibited consistent results and showed that RORA overexpression repressed cell proliferation, migration, invasion and induced apoptosis and cell cycle arrest in glioma." (PMID 34479497, 2021). "It has been found that in glioma, miR-18a can inhibit cell proliferation by regulating RORA." (PMID 38879468, 2024). "In addition, RORA was a target of miR-1290, and glioma cell malignant phenotypes promoted by miR-1290 restoration were partly blocked by RORA overexpression." (PMID 34479497, 2021). "RORα and RORβ, which modulate the transcription of Bmal1, were observed to be downregulated in gliomas, and this expression profile was prognostic in a cohort of glioma-diagnosed patients suggesting that its function is associated with tumor genesis and progression." (PMID 34361055, 2021). "However, the interactions among circRELN, miR-1290 and RORA need to be clarified to determine the action of circRELN in glioma." (PMID 34479497, 2021). "In the present study, we furtherly found that RORA expression in GBM was lower than in lower-grade glioma, indicating that RORA may inhibit the invasion and migration in GBMs." (PMID 34408982, 2021). "Besides, we further conducted a Kaplan-Meier survival analysis to evaluate whether the expressions of RORA affected the prognoses of glioma patients." (PMID 34408982, 2021). "We found significant differences in the expression levels of ADD2, CTC1, SRCIN1, RORA, and ULK2 genes in gliomas of different grades, excluding VPS4A." (PMID 39698112, 2024).
glioma (continued). "MiR-18a downregulates RORα through the TNF-α-mediated NF-κB signaling pathway, inhibiting glioma proliferation and tumor development." (PMID 38725854, 2024). "The differential expression of CCGs in glioma grading confirmed that cluster I genes (ARNRL, NPAS2, and TIMELESS) and CRY1, with cluster II genes (CRY2, DBP, NR1D1, NR1D2, PER2, PER3, and RORA) showed significantly opposite expression trends in brain tissues." (PMID 35832846, 2022). "The correlations between RORA and TGF-β1 expressions in 87 cases of clinical glioma specimens were then detected by RT-qPCR, which showed significant negative correlations in lower-grade gliomas and GBMs." (PMID 34408982, 2021). "The BTSCs also showed ⩾100-fold increase in the transcription of TLX and HNF4α, and between 10- and 100-fold increase in PXR, RORα, RORγ, NORI and LRH compared with glioma cells." (PMID 21224854, 2011). "Furthermore, survival analysis revealed that patients with glioma with high expression of ADD2, CTC1, SRCIN1, VPS4A, ULK2, excluding RORA, had a longer overall survival than those with low expression." (PMID 39698112, 2024). "Similarly, disease-free survival was found to be longer in patients with glioma with high expression of ADD2, CTC1, SRCIN1, RORA, VPS4A, and ULK2 than in those with low expression." (PMID 39698112, 2024). "Besides, the expression of eight CCGs (CRY2, DBP, NR1D1, NR1D2, PER2, PER3, RORA, and TIMELESS) was negatively regulated by methylation and positively regulated by CNV in glioma, which is consisting with previous studies that DNA methylation and CNV can promote abnormal gene expression." (PMID 35832846, 2022).